S100A8 (S100 calcium binding protein A8)
Diseases named in the same sentence as S100A8 in open-access papers (continued):
Sharing a sentence is not in itself a finding about the gene and the disease.
colitis (continued). "In this study, we confirmed the pharmacological effects of S100A8 in UC and intraperitoneally administered recombinant rat S100A8 (rr-S100A8) to rats with DSS-induced experimental colitis." (PMID 39596871, 2024). "Specifically, in TNBS-induced colitis, Cd44, Numa1, S100a8, S100a9, Timp1 and Xbp1 were more highly expressed, while Cidec and Rag1 were less expressed." (PMID 38778086, 2024). "In animal experiment 2, the peritoneal administration of rr-S100A8 after the onset of UC resulted in a slight histopathological enhancement in colitis." (PMID 39596871, 2024). "This strongly indicates that rr-S100A8 reduces excessive activation of immune cells in the colon tissue and can serve as an immunosuppressive agent in rats with experimental colitis." (PMID 39596871, 2024). "Antibody treatment with anti-S100A8/9 has been proven effective in mouse models of colitis, acute myocardial infarction, and pancreatitis, which reveals the effect of anti-S100A8/9 antibody treatment on inflammatory diseases." (PMID 36768371, 2023). "During colitis, neutrophils abundantly express and secrete S100A8 protein, which forms an S100A8/S100A9 heterodimer (also called calprotectin; a non-invasive biomarker in IBD)." (PMID 37006281, 2023). "Damage-associated molecular patterns S100A8 and S100A9 play an important role in colitis by binding to their pattern recognition receptors PRR, especially TLR4." (PMID 38273841, 2023). "We confirmed upregulation of Lcn2 and S100A9 transcripts and measured increased Lcn2 and S100A8/A9 protein expression in brains isolated from mice with colitis, albeit expression is markedly less than the levels detected in mice injected with LPS." (PMID 34758843, 2021). "RNF5 was shown to restrict colitis in an S100A8-dependent manner, as RNF5 deficient mice demonstrated S100A8 accumulation that induced colitis, which was abrogated by S100A8-neutralizing antibodies." (PMID 34356615, 2021). "The increased expression of S100a8/a9 in Dok3−/− colons during DSS-induced colitis was further validated by reverse transcription-quantitative polymerase chain reaction (RT-qPCR) analysis." (PMID 34743196, 2021). "In our study, excessive production of S100a8/9 by neutrophils in Dok3−/− mice consequently promoted microbiome dysbiosis in their gut, resulting in mutant mice succumbing to exacerbated colitis upon DSS treatment." (PMID 34743196, 2021). "This suggests that immune cells in Dok3−/− colon contributed to S100a8/9 hyper-production, and hence microbial dysbiosis and enhanced inflammation, during colitis." (PMID 34743196, 2021). "For example, inhibition of PARP dampens inflammation associated with colitis, while elevated levels of CRP and S100A8, for example, have been associated with inflammatory pathologies." (PMID 30814064, 2019). "Consistent with antimicrobial activity in the lumen of the gut during colitis, we observed significantly higher expression of the AMPs S100a8, S100a9, S100a14 and Ltf as well as Nos2 in colon contents." (PMID 27003245, 2016). "Increased transcription of AMP transcripts, such as S100a8, S100a9, S100a14 and lactoferrin (Ltf) in the lumen of the gut during colitis suggests a required ability for commensal microbes to withstand antimicrobial activity during inflammation." (PMID 27003245, 2016). "The expression of S100A8 was also found to be up-regulated in the trinitrobenzene sulfonic acid (TNBS)-induced colitis rat model and T-cell-mediated colitis in SCID mice." (PMID 26085826, 2015). "To determine whether elevated S100A8 expression contributes to the severe colitis phenotype in Rnf128−/− mice, we blocked S100A8 with its neutralizing antibodies in the DSS-induced colitis model." (PMID 39809743, 2025). "Moreover, the administration of an S100A8 neutralizing antibody mitigated the development of colitis and improved survival in DSS-treated Rnf128−/− mice." (PMID 39809743, 2025).
colitis (continued). "Given the colitis-promoting effects of S100A8, targeting S100A8 may be an attractive therapeutic strategy for IBD." (PMID 39809743, 2025). "The DAI score results indicate that rr-S100A8 may serve as an immunosuppressive drug that regulates excessive immune responses in the colon tissues of rats with experimental colitis." (PMID 39596871, 2024). "This indicates that rr-S100A8 suppresses the progression of experimental colitis." (PMID 39596871, 2024). "In a recently published study, DSS-induced colitis found upregulation of inflammatory-related proteins S100A8, S100A9 (also known as myeloid related protein (MRP) 8 and MRP14), and lipocalin-2 (Lcn2, also known as neutrophil gelatinase-associated lipocalin) in the brain." (PMID 34983592, 2022). "Moreover, RNF5-low/S100A8-high sections of the gut epithelium of colitis patients correlated with severe inflammation." (PMID 34356615, 2021). "Therefore, the peritoneal administration of rr-S100A8 may be partially effective for remission in experimental colitis, although the reason for its limited remission remains unclear." (PMID 39596871, 2024). "Moreover, colitis-induced LI shortening was strongest in former MN mice, which could also be significantly mitigated by a neonatal S100a8 treatment." (PMID 39366940, 2024). "Therefore, rr-S100A8 may suppress the excessive activation of neutrophils, monocytes, MΦ, and lymphocytes in the blood, thereby alleviating experimental colitis." (PMID 39596871, 2024). "In addition, we speculated that the administration of rr-S100A8 to rats would improve the pathogenesis of experimental colitis." (PMID 39596871, 2024). "In line with their greater sensitivity to DSS-induced colitis, we saw a loss of protective intestinal bacterial genera such as Bacteriodes in untreated Dok3−/− mice, which correlates with what was observed in the microbiota obtained from IBD patients with elevated fecal levels of S100a8/9." (PMID 34743196, 2021). "In addition to being highly variable, S100A8 correlated poorly with colitis scores." (PMID 31840738, 2020). "This is not surprising, as one could expect that by protecting mice from developing colitis, BI119 would be acting not only against direct targets of RORγt (such as IL17A), but also on the expression of indirect targets (IFNG or S100A8) associated with the inflammatory response in colitis." (PMID 30405600, 2018). "S100A8 and S100A9 have been demonstrated to disturb the intestinal mucosal homeostasis, promoting the advancement of colitis by activating pro-inflammatory signaling pathways." (PMID 39796257, 2025). "Functional profiling revealed that human S100A8 and S100A9 homodimers enhanced activation of cluster of differentiation 4+ and 8+ T cells, which promoted experimental colitis." (PMID 41295942, 2025). "In contrast, the increased expression of S100A8 in the intestinal tract resulted in helper T cell hyperactivity, thereby exacerbating DSS-induced murine colitis." (PMID 39596871, 2024). "In murine colitis and CAC models, elevated serum concentrations of S100A8 and S100A9 were detected, in addition to notable enhancements in their interaction with PRRs, especially TLR4, and RAGE." (PMID 38892354, 2024). "The gut mucosal DAMPs S100A8 and S100A9 have recently come to be recognized as pivotal agents in the pathogenesis of colonic inflammation." (PMID 38892354, 2024). "Increased S100A8 levels in the intestinal tract accelerate helper T cell hyperactivity and exacerbate DSS-induced colitis." (PMID 39596871, 2024). "The rats that developed colitis after regularly drinking 3% dextran sulfate sodium (DSS), and those that were administered rat recombinant S100A8 (rr-S100A8) in addition to DSS were named the DSS + A8 group." (PMID 39596871, 2024). "The expression of S100a9, S100a8, Lcn2, Il1f9, Mmp8, and Mmp9 were significantly increased in CD45+ cells from Il17b-/- colitis mice (P < 0.05)." (PMID 36814913, 2023).
colitis (continued). "Of note, host antimicrobial gene expression levels (Lcn2, S100a8, S100a9) were similarly upregulated in all DSS-treated mice, and all DSS-treated mice developed similar levels of colitis, as shown by histopathology evaluation of the distal colon." (PMID 34853318, 2021). "We focused on innate immune instead of adaptive cells since S100a8/9 proteins are expressed predominantly by innate cells, and DSS-induced colitis is a model for the study of innate immune mechanisms." (PMID 34743196, 2021). "Our data demonstrate a significant increase in the inflammatory chemokine, KC, as well as inflammatory biomarkers, S100A8 and S100A9, in the colons, serum and brains of mice with colitis." (PMID 34758843, 2021). "As expected, DSS colitis significantly increased the expression of mature miR-146a, MCP-1, S100A8 and IFNγ." (PMID 30478292, 2018). "This is because treatment with rr-S100A8 did not significantly suppress diarrhea and hemorrhage in the experimental UC rats in comparison to the spontaneous remission of colitis when 3% DSS was replaced with DW in the experiment." (PMID 39596871, 2024). "However, despite the induction of colitis by DSS, its pathogenesis in transgenic animals (Tg-S100A8) was alleviated." (PMID 39596871, 2024). "The body weights remained low even after rr-S100A8 administration, indicating that rr-S100A8 is not always effective in treating experimental colitis because of toxicity or poor nutrient absorption." (PMID 39596871, 2024). "Whilst S100A8 and S100A9 may play a central role in propagating neuroinflammation in colitis models, it has been suggested that NLR family pyrin domain containing 3 (NLRP3) protein activation may be involved." (PMID 34983592, 2022). "Consequently, upon blockage of S100a8/9 binding to RAGE or TLR4 receptor through administration of FPS-ZM1 or Paquinimod, we were able to rescue colitis severity in Dok3−/− mice, indicating the importance of S100a8/9 in promoting colonic inflammation." (PMID 34743196, 2021). "As expected, colitis induced by CD4+CD45RBhigh T cells in immune-depleted mice was associated with a significant increase in Th17 genes, IFNG, IL10 as well as S100A8 and S100A9 (data not shown)." (PMID 30405600, 2018). "Additionally, regardless of the presence or absence of rr-S100A8 administration, no significant alterations were observed in the colon length, indicating that rr-S100A8 did not participate in the remission of experimental colitis." (PMID 39596871, 2024). "Since S100a8/9 expression has been shown to correlate with clinical severity in IBD patients, and their neutralization can attenuate colitis pathology, targeting JAK2-STAT3 signaling axis may represent potential therapeutic strategies to regulate gut microbiome and inflammation." (PMID 34743196, 2021). "Because we detected S100A8/A9 upregulation in the serum and brains in mice with colitis, we hypothesized that inhibition of S100A9-signaling would reduce the neuroinflammatory signature in mice with colitis." (PMID 34758843, 2021). "Although the difference in the serum concentration of r-S100A8/A9 between the UCR and TMR was only on day 10, the serum level of the heterodimer in the UCR was significantly higher than that in the TMR, indicating that the heterodimer is apparently a sensitive biomarker for experimental colitis." (PMID 32140589, 2020). "Therefore, S100A8 does not directly repair experimental colitis in rats but may contribute to the negative regulation of the excessive activation of immune cells associated with acute inflammation." (PMID 39596871, 2024).
Obesity (43 papers, 2009 to 2026). Accumulation of substantial excess body fat. "Of particular note is also the close association of S100A8 with four major metabolism-related diseases, namely diabetes, obesity, hypertension and hyperlipidaemia, and the important role it plays in their pathogenesis." (PMID 37497233, 2023). "Because obesity, diabetes, hypertension and hyperlipidemia were the core of MetS syndrome, we verified the level of expression and diagnostic value of S100A8 in these four metabolic related diseases." (PMID 37497233, 2023). "Obesity was clearly associated with higher circulating levels of triglycerides (p < 0.01) and with the intestinal damage biomarkers S100A8 (p < 0.001) and lactoferrin (p < 0.05)." (PMID 36831381, 2023). "The S100A8/A9 complex is implicated in the pathophysiology of obesity-promoting macrophage-based inflammation." (PMID 37372165, 2023). "The S100 protein family members, S100A4, S100A8/A9 heterodimer, and S100B have all been implicated in the pathophysiology of obesity-associated inflammation via their interaction with RAGE." (PMID 34204735, 2021). "Our study revealed that elevated levels of S100A8/S100A9 were closely associated with the development of obesity, while hypomethylation of the promoter region resulted in upregulation of S100A8/S100A9 expression." (PMID 34055926, 2021). "S100A8 mRNA expression levels are increased during obesity, but weight loss restores the values observed in the control patients group." (PMID 31941045, 2020). "Activated neutrophils and monocytes are the main sources of extracellular S100A8/A9 and diabetes, dyslipidemia, obesity, and smoking are associated with elevated circulating protein levels." (PMID 24453429, 2013). "Diabetes mellitus, obesity, smoking, and hyperlipidemia are traditional CV risk factors that have been associated with increased levels of S100A8/A9 in plasma." (PMID 24453429, 2013). "The levels of circulating S100A8/A9 in humans strongly correlate to blood neutrophil counts and are increased by traditional cardiovascular risk factors such as smoking, obesity, hyperglycemia, and dyslipidemia." (PMID 24453429, 2013). "S100A9 and S100A8 are associated with the prognosis of diabetes mellitus and obesity." (PMID 36837510, 2023). "In particular, S100A8/A9 has emerged as a key myeloproliferative factor in diabetes and obesity, and as such, treatment with inhibitors of S100A8/A9 in addition to current therapies may reduce CVD risk in these patient groups." (PMID 31249530, 2019). "In addition, increased gene expression of S100A8 and S100A9 in visceral AT and increased concentrations of S100A8/A9 complexes in the circulation have been observed in obese patients and correlated with the obesity associated low-grade inflammation in the patients." (PMID 35198063, 2022). "In a previous study, investigating mechanisms of increased skin inflammation in mouse models of obesity including db/db mice, we described an increased and prolonged expression of the alarmins, S100A8 and S100A9, during diabetic wound healing in db/db mice." (PMID 39337466, 2024). "The outcome indicated that S100A8 expression levels were significantly higher in four metabolic related diseases, namely obesity, diabetes, hypertension and hyperlipidaemia, than in the control group." (PMID 37497233, 2023). "In a report on human and mice obesity, serum calprotectin correlated with the visceral and subcutaneous fat area and body mass index in men, and S100A8 and S100A9 were overexpressed in adipose tissue in mice." (PMID 37372165, 2023). "Of note, we observed a similar dysregulation of S100A8 and S100A9 and M2-like macrophage markers as in the obesity-associated skin inflammation model." (PMID 35198063, 2022). "In this study, Protein S100-A8 was also up-regulated in the saliva of pregnant women with obesity and periodontitis, and after delivery the level of this protein increased even more in this group." (PMID 36355174, 2022).
Obesity (continued). "Certain S100 proteins including S100A8 and S100A9 have been associated with pathophysiological processes in obesity." (PMID 35198063, 2022). "Some S100 members (e.g., S100A4, S100A8/A9, S100A12 and S100B) have also been suggested to represent potential biomarkers of NAFLD-associated disorders such as obesity, type 2 diabetes, IR and inflammation." (PMID 36232334, 2022). "Certain S100 proteins, namely S100A4, S100A8/S100A9 heterodimer, and S100B, have been implicated in the pathophysiology of obesity-promoting macrophage-based inflammation via toll-like receptor 4 and/or receptor for advanced glycation end-products ligation." (PMID 35328627, 2022). "Altogether, these results outline a pivotal role for GIP in balancing fat depot type 2 immune networks during the development of obesity, at least partially through its restraining of the immune cell-derived S100A8/A9." (PMID 33717200, 2021). "In conclusion, we identified GIPR signaling as an important regulator of type 2 immunity networks in epiWAT and energy expenditure in ingWAT and a gatekeeper of the unrestrained activity of S100A8/A9 in myeloid cells during obesity." (PMID 33717200, 2021). "In the epiWAT from mice with obesity, GIP plays an important role in restraining the production of S100A8/A9 in ATMs, and the deficiency in GIPR in myeloid cells augments myelopoiesis and accumulation of S100A8/A9+ neutrophils and ATMs in the epiWAT." (PMID 33717200, 2021). "Consistent with the obtained proteomic data showing evidence of the down-regulation of proteins related to the immune system after BS, S100A8 mRNA expression levels increased with obesity and decreased after BS on aSAT." (PMID 31941045, 2020). "It is known that chronic low-grade inflammation of AT plays a crucial role in the pathophysiology of obesity and increased expression of AT S100A8 can trigger macrophage mobility resulting in the progression of chronic inflammation in situ." (PMID 31941045, 2020). "We have previously shown that S100A8/A9 is responsible for inducing myelopoiesis in both diabetes and obesity; however, the mechanism by which S100A8/A9 mediates this process differs between disease contexts, which we discuss below." (PMID 31249530, 2019). "In metabolic inflammatory diseases, such as gout, diabetes, and obesity, S100A8/A9 is secreted and distributed in a disease-specific manner, and elevated levels of S100A8/A9 have been detected in sera and inflammatory sites." (PMID 29942307, 2018). "In 3T3-L1 adipocytes, we evaluated the effect of organotins on the expression of inflammatory response-related genes such as Lgals9, Fn1, Dcn, Vcam1 and S100a8, which are accordingly related to obesity and insulin resistance." (PMID 28824431, 2017). "Most recently, upregulated S100A8 expression levels were shown to contribute to the very early stage of pathogenesis of obesity and induce local inflammation." (PMID 27999286, 2016). "We showed that the overexpression of S100A8/A9 during inflammatory conditions in the skin of mice with obesity impairs appropriate macrophage activation and the polarization required for inflammatory resolution and tissue repair and contributes to impaired wound healing in type 2 diabetic mice." (PMID 39337466, 2024). "Furthermore, in the context of obesity, S100a8/S100a9, which are significant hysteresis genes recognized as damage-associated molecular patterns (DAMPs), are presumed to trigger ATM-mediated immune responses." (PMID 38173717, 2023). "Importantly, we demonstrated that the S100A8 inhibitor, paquinimod, diminished S100A8+ immune cells in BAT, therefore ameliorating obesity-associated metabolic dysfunction in aged mice." (PMID 37268694, 2023). "In the validation of the dataset for the four metabolism-related diseases (obesity, diabetes, hypertension and hyperlipidaemia), S100A8 was expressed at higher levels in the disease group and also had a higher diagnostic value for the four metabolism-related diseases." (PMID 37497233, 2023).